SP4 (Sp4 transcription factor)
Diseases named in the same sentence as SP4 in open-access papers (continued):
Sharing a sentence is not in itself a finding about the gene and the disease.
Autoimmunity (1 paper, 2011). The occurrence of an immune reaction against the organism's own cells or tissues. "Similarly, defects in the thymocytes-epithelial cells interaction in the medulla, such as Aire and Relb deficiency, result in the SP3-to-SP4 blockage and autoimmunity in the periphery." (PMID 22022412, 2011).
brain tumors (1 paper, 2019). "Among the members of the specificity protein (Sp) family, both Sp1 and Sp4 were obviously increased in brain tumor compared with normal brain." (PMID 31717924, 2019). "To understand whether Sp4 is overexpressed in GBM, we estimated the level of Sp4 in the tissue array including brain tumor and normal brain tissues using immunohistochemical staining." (PMID 31717924, 2019). "Before our study showing that Sp4 is involved in the drug resistance of GBM, there was no known role for Sp4 in brain tumors." (PMID 31717924, 2019).
Cognitive impairment (1 paper, 2024). Abnormal cognition is characterized by deficits in thinking, reasoning, or remembering. "Additionally, the expression of transcription factor Sp4 was found to increase, which regulated the gene Ablim3 associated with cognitive impairment in the InN1 subpopulation." (PMID 39635132, 2024).
depression (1 paper, 2013). "Interestingly, human SP4 gene has been found to be one of the leading candidate genes associated with major depression." (PMID 23823008, 2013). "Identification of these SP4 SNPs may help predict ketamine efficacy in treatment of depression." (PMID 23823008, 2013).
emphysema (1 paper, 2015). "Therefore, C-ICD may be generated in lung epithelial cells under specific pathological conditions where SP4 ectodomain shedding is induced, such as emphysema and interstitial pneumonia." (PMID 26259600, 2015).
HIV-1 infection (1 paper, 2008). The type species of lentivirus and the etiologic agent of acquired immunodeficiency syndrome (AIDS). "Except for 2 h SP4-2 pretreatment of cells that was done at 37°C to allow for SP4-2-CD4 interaction, we performed all the subsequent steps, including HIV-1 infection at 4°C." (PMID 18197976, 2008).
juvenile dermatomyositis (1 paper, 2024). Juvenile dermatomyositis (JDM) is the early-onset form of dermatomyositis (DM), a systemic, autoimmune inflammatory muscle disorder, characterized by proximal muscle weakness, evocative skin lesion, and systemic manifestations. "Anti-CCAR1 autoantibody frequency was 9% of an anti-TIF1γ positive US juvenile dermatomyositis (JDM) cohort screened by ELISA, and was associated with a lower frequency of cutaneous ulceration and similar clinical features to anti-Sp4 autoantibodies." (PMID 39514366, 2024).
leukemia (1 paper, 2020). A malignant (clonal) hematologic disorder, involving hematopoietic stem cells and characterized by the presence of primitive or atypical myeloid or lymphoid cells in the bone marrow and the blood. "Among the E/R+ TF network, ELK3 and SP4 have been reported to confer risk of leukemia development in GWAS." (PMID 33218352, 2020).
Listeria monocytogenes infection (1 paper, 2011). "When the same number of purified SP3, SP4 thymocytes and naïve CD4+ T cells from C57BL/6 Ly5.1 mice were adoptively transferred into congenic Ly5.2 mice, similar levels of donor T cell activation were observed seven days after Listeria monocytogenes infection of the host." (PMID 22022412, 2011).
male infertility (1 paper, 2020). The inability of the male to effect fertilization of an ovum after a specified period of unprotected intercourse. "Mice with null mutation in Sp4 gene exhibited a high mortality rate after birth, growth retardation, pronounced delay in sexual maturation, male infertility and underdeveloped uteri in females, indicating the essential role of Sp4 in growth, puberty and reproduction." (PMID 33152014, 2020).
myositis (1 paper, 2024). "We aimed to determine the frequency of anti-Sp4 and anti-CCAR1 in UK anti-TIF1γ-positive myositis populations and report any observed clinical associations, including cancer risk." (PMID 39514366, 2024). "This study aims to identify the frequency of anti-Sp4 and anti-CCAR1 in adult and juvenile UK anti-TIF1γ-positive myositis populations and report clinical associations." (PMID 39514366, 2024). "Unexpectedly, we found the frequency of anti-Sp4 to be much lower in UK myositis populations compared with data published on US cohorts, 4% vs 43% in adults and 0% vs 20% in children." (PMID 39514366, 2024). "We were surprised therefore to observe a much lower frequency of anti-Sp4 and anti-CCAR1 autoantibodies in UK adult anti-TIF1γ positive myositis participants." (PMID 39514366, 2024). "Anti-Sp4 and anti-CCAR1 autoantibodies are less common in the adult UK anti-TIF1γ-positive myositis population compared with published data from the USA, limiting their use as biomarkers for cancer risk." (PMID 39514366, 2024). "Nineteen (37%) anti-TIF1γ positive UK adult myositis patients had cancer; neither of the two patients with anti-Sp4 autoantibodies and 25% (2/8) of anti-CCAR1 autoantibody-positive patients had cancer." (PMID 39514366, 2024).
neuroblastoma (1 paper, 2019). Neuroblastoma (NB) is the most common solid, extracranial childhood tumor. "Accordingly, the nuclear content of Sp4 is significantly higher in primary neurons than in neuroblastoma cells." (PMID 31231235, 2019). "However, the discussed pathways are documented only in neuroblastoma N2a cells, but in primary neurons Sp1 is functionally replaced with another factor, Sp4, specific for the neurons and testicular cells." (PMID 31231235, 2019).
Psychosis (1 paper, 2015). "We found that SP4 S770 phosphorylation was significantly increased in lymphocytes in first-episode psychosis compared to controls and decreased in patients treated with lithium compared to patients who did not receive lithium." (PMID 25915526, 2015). "Here we report that SP4 S770 phosphorylation is increased in peripheral lymphocytes of first-episode psychosis." (PMID 25915526, 2015). "Reduced levels of SP4 protein have recently been reported in peripheral blood mononuclear cells in first-episode psychosis." (PMID 25915526, 2015). "An increasing body of evidence indicates that SP4 transcription factor has a role in complex psychotic disorders through its regulation of a large network of genes, including components of NMDAR signaling pathways." (PMID 25915526, 2015). "Influence of demographic and clinical characteristics on pSP4/SP4 ratio in peripheral blood mononuclear cells in first-episode psychosis and control subjects." (PMID 25915526, 2015). "The findings presented here indicate that SP4 S770 phosphorylation is increased in lymphocytes in first-episode psychosis which may be reduced by lithium treatment in patients." (PMID 25915526, 2015). "Based on these previous observations, we hypothesized that SP4 S770 phosphorylation may be altered in peripheral blood mononuclear cells in first-episode psychosis patients." (PMID 25915526, 2015). "This pilot study suggests that S770 SP4 phosphorylation could be a peripheral biomarker of psychosis, and may be regulated by lithium treatment in first-episode psychosis." (PMID 25915526, 2015). "The aim of this study was to investigate whether SP4 S770 phosphorylation is increased in lymphocytes of first-episode psychosis patients and the effect of lithium treatment on this phosphorylation." (PMID 25915526, 2015). "Peripheral blood screening of SP4 phosphorylation levels may be a useful peripheral biomarker of psychosis and potentially regulated by lithium treatment in the early stages of psychosis." (PMID 25915526, 2015). "Thus, our findings suggest that SP4 phosphorylation is a potential biomarker for first-episode psychosis which may be regulated by lithium treatment." (PMID 25915526, 2015). "The main aim of this study was to investigate whether phosphorylation at SP4 S770 was increased in peripheral blood mononuclear cells in first-episode psychosis, how it related to SP4 protein abundance, and if this phosphorylation could be modulated by treatment with lithium." (PMID 25915526, 2015). "A cross-sectional study of S770 phosphorylation relative to total SP4 immunoreactivity using specific antibodies in peripheral blood mononuclear cells in first-episode psychosis patients (n = 14, treated with lithium or not) and matched healthy controls (n = 14) by immunoblot was designed." (PMID 25915526, 2015). "However, whether SP4 phosphorylation is increased in early psychosis, and whether this correlates with reduced Sp4 levels in lymphocytes of FEP patients is not known." (PMID 25915526, 2015). "However, we cannot rule out the possibility that SP4 S770 phosphorylation may be dynamic and could change over the course of the disease in PBMC, as we also cannot predict how peripheral levels of phosphorylated SP4 relate to the actual levels in the different brain areas involved in psychosis." (PMID 25915526, 2015).
retinal degeneration (1 paper, 2007). Degeneration of the retina. "The purpose of this work, therefore, was to investigate possible mutations in SP4 in a cohort of patients affected with different forms of retinal degenerations." (PMID 17356515, 2007). "Since mutations in NRL and CRX are involved in inherited retinal degenerations, SP4 was considered a good candidate for mutation screening in patients with this type of diseases." (PMID 17356515, 2007). "Because of its specific involvement in transcription of rod genes and because of the history of transcription factor mutations causing retinal degeneration, we considered SP4 a good candidate gene to screen for missense mutations in patients with various forms of retinal degeneration." (PMID 17356515, 2007). "Therefore, we considered the human SP4 gene a good candidate for the site of missense mutations causing retinal degeneration, given its involvement in the transcription of several photoreceptor genes including PDE6B and the phenotype of the Sp4 knockout mouse." (PMID 17356515, 2007). "To this end, we screened the 6 exons of the SP4 gene in a group of 270 patients with various forms of retinal degeneration that had been screened previously for a number of photoreceptor genes." (PMID 17356515, 2007). "Even though 2/3 of mice born with the Sp4 gene deleted die within the first four weeks of life, the surviving mice have many abnormalities including severe retinal degeneration (our data, not shown)." (PMID 17356515, 2007).
seminoma (1 paper, 2025). A radiosensitive malignant germ cell tumor found in the testis (especially undescended), and extragonadal sites (anterior mediastinum and pineal gland). "In contrast, the right and left specimens of the two synchronous bilateral seminomas (SP2 and SP4) do not cluster together, suggesting that their PGC formed after the separation into the right and left gonadal ridges occurred." (PMID 40358182, 2025).
trisomy 21 (1 paper, 2024). A chromosomal disorder consisting of the presence of an extra chromosome 21. "A detailed sub-analysis of the samples from children with trisomy 21 reveals higher DP cell frequencies compared to samples from children with cyanotic CHD and, concomitantly, lower SP4 and Treg frequencies." (PMID 38393459, 2024).
cancer (38 papers, 2012 to 2025). A tumor composed of atypical neoplastic, often pleomorphic cells that invade other tissues. "Anti-TIF1γ autoantibodies are strongly associated with cancer and often co-occur with autoantibodies against other proteins such as SP4 and CCAR1." (PMID 40568657, 2025). "Due to the small numbers of anti-CCAR1 and anti-Sp4 autoantibodies identified, this study is underpowered to draw firm conclusions on the influence of these autoantibodies on cancer risk and other clinical features." (PMID 39514366, 2024). "In contrast, SRSP was highly expressed in CRC cells, and it strengthened the recognition and interaction of SRSF3 on exon 3 of Sp4 to promote exon 3 inclusion, which induced cancerous splicing variant L-Sp4 formation, eventually accelerating the pace of cancer progression." (PMID 36358616, 2022). "While anti-CCAR1 and anti-Sp4 appear to be the most common ‘cancer-modifier’ autoantibodies in anti-TIF1γ-positive DM, others have been described and an increasing diversity of the autoimmune response appears to be associated with a reduced likelihood of cancer emergence." (PMID 39636383, 2024). "Interactions of NR4A2 and NR4A3 with Sp1/Sp4 to activate or deactivate gene expression have not been characterized; however, there is considerable evidence that NR4A1 interacts with Sp1 and Sp4 to regulate several genes in cancer cell lines." (PMID 39858066, 2025). "This autosis-centric activity enables Tat-SP4 to overcome the dual-natured limitation of autophagy in tumorigenesis and exert a broad anti-proliferative effect in many cancer types." (PMID 41471037, 2025). "High levels of Sp1, Sp3, and Sp4 contribute to cancer cell development, survival, and migration to tissues, including the pancreas." (PMID 40758706, 2025). "Specificity proteins (Sp), members of the Sp/Kruppel-like factor family, demonstrate elevated expression patterns across various tumor and cancer cell lineages, with particularly pronounced expression observed for Sp1, Sp3, and Sp4." (PMID 41007866, 2025). "For CNV deletions, only three genes (KCND2, SDK1, SP4) displayed more than three instances across different BD‐cancer patients." (PMID 39140252, 2025). "Ligands for PPARƔ, AR, PR and RARα activate p21 expression in cancer cells through interactions of NR/Sp1 or NR/Sp4 with two or more members of the Sp1–6 binding sites in the proximal region of the p21 gene promoters." (PMID 39858066, 2025). "Results reported in different studies show that autoantibodies against Sp4 and CCAR1 are associated with a reduced risk of cancer in adults with anti-TIF-1γ -positive DM." (PMID 39169942, 2024). "Two novel autoantibodies, anti-Sp4 and anti-CCAR1, have recently been described which co-occur with anti-TIF1γ and significantly attenuate the cancer risk to a level comparable to that of the general population." (PMID 39636383, 2024). "In this review, the role of Sp1, Sp3 and Sp4 in the development of cancer and their regulation of pro-oncogenic factors and pathways is reviewed." (PMID 36982239, 2023). "SP1 is critical for early embryonic development, but its expression decreases with age and there is evidence that the transformation of normal cells to cancer cells is associated with the upregulation of SP1, SP3, and SP4." (PMID 37998757, 2023). "A detailed study of the role of Sp1, Sp3 and Sp4 in cancer was investigated in multiple cancer cell lines by individual knockdown of the three genes and their combination coupled with analysis of the resulting functional and genomic effects and their overlap." (PMID 36982239, 2023). "Future studies are required to further characterize possible autosis in Tat-SP4-treated cancer cells." (PMID 36765914, 2023). "Sp4 also regulates ANGPTL4 and downstream EGFR/AKT/4E-BP1, which is associated with temozolomide resistance and expression of cancer stem cell markers." (PMID 36982239, 2023).
cancer (continued). "There is increasing evidence that Sp1, Sp3 and Sp4 play an important role in multiple cancers and their prognostic importance spans their functional pro-oncogenic activities alone and in combination with miRNAs and lncRNAs." (PMID 36982239, 2023). "The specificity protein (Sp) transcription factors (TFs) Sp1, Sp2, Sp3 and Sp4 exhibit structural and functional similarities in cancer cells and extensive studies of Sp1 show that it is a negative prognostic factor for patients with multiple tumor types." (PMID 36982239, 2023). "The pro-oncogenic functions of Sp1, Sp3 and Sp4 in cancer cell lines were studied in knockdown studies where silencing of each individual Sp TF decreased cancer growth, invasion and induced apoptosis." (PMID 36982239, 2023). "Despite these facts, anticancer agents that specifically target SpTFs are not being developed currently for clinical applications, even though several small molecules that are used for cancer and other chemotherapies also downregulate/degrade Sp1, Sp3 and Sp4." (PMID 36982239, 2023). "With few exceptions, lncRNA/miRNA pathways that lead to higher expression of Sp1, Sp3 and Sp4 result in downstream activation of pro-oncogenic genes/pathways, indicating that drugs targeting ncRNAs or Sp TFs should be highly effective anti-cancer agents." (PMID 36982239, 2023). "Transfection of MCF-7 and MDA-MB-231 cancer cells with miRNA-20a, miRNA-106a and miRNA-106b antagomirs led to evident suppression in the levels of Sp1, Sp3, Sp4 and EZH2, but, simultaneously, there was an increase in the levels of ZBTB4." (PMID 36615262, 2022). "Normally, Sp1 and Sp3 are ubiquitously expressed in cells, and Sp4 expression is restricted to neuronal cells where it acts as a transcription activator; however, Sp4 expression has been found in many cancer cell lines such as the LNCaP." (PMID 35018219, 2022). "Similar to Sp1 and Sp4, Sp3 is often highly expressed in cancer cells, and knockdown of Sp3 in these cancer cells dramatically reduced cell proliferation and survival." (PMID 35019687, 2022). "Some miRNAs over expressed in cancer, such as members of the miR-17-92 (miR-20a/miR-17-5p) and miR-27a clusters indirectly maintain high expression of Sp1, Sp3 and Sp4." (PMID 32050628, 2020). "An antipsychotic drug, penfluridol, is currently used as an anti-cancer drug since it can downregulate the TFs like Sp1, Sp3, and Sp4." (PMID 32050495, 2020). "According to a few studies, BA inhibits the growth of cancer cells by stimulating proteasome-dependent downregulation of Sp1, Sp3, and Sp4." (PMID 32050495, 2020). "Inhibitors abrogating FLI1, MEF2C, ELK3, or SP4 activation have been previously shown to have efficacy in different cancers." (PMID 33218352, 2020). "A recent report showed that MALAT-1 is an Sp1-regulated gene and we therefore determined if ROS-inducing anticancer agents that downregulate Sp1, Sp3 and Sp4 in pancreatic and other cancer cell lines also decrease MALAT-1 expression." (PMID 29389953, 2018). "Studies in cancer cell lines show that Sp1, Sp3 and Sp4 are highly expressed, and RNA interference (RNAi) studies indicate that Sp transcription factors regulate genes associated with cell proliferation, survival and migration/invasion [reviewed in 14]." (PMID 26967243, 2016). "The functional and genomic effects of Sp1, Sp3 and Sp4 were investigated by RNAi in several different cancer cell lines." (PMID 26967243, 2016). "Sp1, Sp3 and Sp4 are overexpressed in many different cancer cell lines and high expression of Sp1 in tumors is a negative prognostic factor for breast, pancreatic, gastric, glioma, prostate and lung cancer patients' survival." (PMID 26317792, 2015). "Sp transcription factors play a role in the proliferation, survival, migration/invasion of several cancer cell lines and we used RNAi to investigate the differential effects of Sp1, Sp3, Sp4 and HULC knockdown on HCC cell proliferation and survival." (PMID 26317792, 2015).